CNNM3 (cyclin and CBS domain divalent metal cation transport mediator 3)
Description:
Probable metal transporter.
Synonyms: ACDP3; SLC70A3
Tractability: Small molecule: a structure with a bound ligand is known. Antibody: UniProt places it where antibodies can reach, with medium confidence; UniProt predicts a signal peptide or a membrane-spanning region; its Gene Ontology location is reachable by antibodies, with medium confidence. PROTAC: ubiquitination databases record sites on it; its protein half-life has been measured.
Gene: Protein-coding gene on chromosome 2 (96,816,245 to 96,835,382, forward strand). Ensembl gene ENSG00000168763.
Subcellular location: Cell membrane
Subcellular location (Human Protein Atlas): Cytosol
Gene Ontology:
Molecular function: protein binding; transmembrane transporter activity
Biological process: magnesium ion homeostasis; transmembrane transport
Cellular component: membrane; plasma membrane
Genetic constraint (gnomAD): Loss-of-function variants: 48 observed, 49.62 expected, observed/expected ratio (o/e) 0.97, 90% interval 0.77 to 1.23. The synonymous counts are far from expectation, so gnomAD's model fits this gene poorly and the ratio says little. Missense variants: 957 observed, 822.18 expected, observed/expected ratio (o/e) 1.16, 90% interval 1.1 to 1.23. Synonymous variants: 507 observed, 396.68 expected, observed/expected ratio (o/e) 1.28, 90% interval 1.19 to 1.38.
Homologues: Orthologues: chimpanzee CNNM3 (99% identical), pig CNNM3 (91% identical), dog CNNM3 (91% identical), rat Cnnm3 (88% identical), mouse Cnnm3 (87% identical), tropical clawed frog cnnm3 (51% identical), Drosophila melanogaster uex (33% identical), Caenorhabditis elegans cnnm-3 (24% identical), Caenorhabditis elegans cnnm-1 (24% identical), Caenorhabditis elegans cnnm-5 (19% identical). Paralogues in human: CNNM1 (47% identical), CNNM2 (45% identical), CNNM4 (43% identical).
Diseases named in the same sentence as CNNM3 in open-access papers:
CNNM3 is named in the same sentence as 26 diseases in open-access papers, as found by Europe PMC text mining. Sharing a sentence is not in itself a finding about the gene and the disease. The quoted sentences say what the papers report.
breast cancer (4 papers, 2016 to 2025). A primary or metastatic malignant neoplasm involving the breast. "In DB-7 mouse mammary tumor cells, overexpression of CNNM3 enhanced anchorage-independent survival in soft agar colony-forming assays." (PMID 40003994, 2025). "In contrast, CNNM3, a homolog with minimal magnesium export capacity, has been described as an oncogene, as its overexpression enhanced tumor growth in a DB-7 mammary cancer mouse xenograft model." (PMID 40003994, 2025). "Our group showed previously that the PRL-2·CNNM3 complex promotes breast cancer progression by regulating magnesium influx." (PMID 26969161, 2016). "It has been suggested that the increased number of TRPM7 promotes metastasis onset while CNNM3 may influence breast cancer development by cooperating with the PRL2 oncogene." (PMID 38732186, 2024). "Thus, to assess the oncogenic capability of the CNNM3 D426A mutant that lost its ability to interact with PRL-2, we generated stable mouse mammary tumor DB-7 cells co-overexpressing CNNM3 WT-v5 or CNNM3 D426A-v5 and luciferase, which were injected in the mammary fat pads of athymic nude female mice." (PMID 26969161, 2016). "Moreover, they have discovered that patients with breast cancer present an increased expression of membrane-bound transporters, specifically TRPM7 and CNNM3, which cooperate to maintain magnesium homeostasis." (PMID 38732186, 2024). "A xenograft tumor assay demonstrated that breast cancer cells that overexpress CNNM3 are more oncogenic compared with CNNM3 G433D, a mutant without ability to bind to PRL-2." (PMID 29859177, 2018). "Here we showed that indeed this molecule blocked the in vitro interaction of PRL-2 with CNNM3 and to also reduced MCF-7 breast cancer cell proliferation, thus corroborating our hypothesis." (PMID 26969161, 2016). "Using a CNNM3 mutant (D426A) that has lost its capacity to interact with PRL-2 or a small molecule inhibitor of the complex formation between these two proteins, we showed that this interaction is important for breast cancer cell proliferation and tumor growth." (PMID 26969161, 2016). "Finally, because molecular modeling showed that the Asp-426 side chain in CNNM3 buries into the catalytic cavity of PRL-2, we showed that a PRL inhibitor could abrogate complex formation, resulting in a decrease in proliferation of human breast cancer cells." (PMID 26969161, 2016).
amelogenesis imperfecta (1 paper, 2019). Amelogenesis imperfecta (AI) represents a group of developmental conditions affecting the structure and clinical appearance of the enamel of all or nearly all the teeth in a more or less equal manner, and which may be associated with morphologic or biochemical changes elsewhere in the body. "cnnm-3/ CNNM4 is a metal ion transporter, and mutations in CNNM4 cause Jalili syndrome, a disorder that includes retinal cone-rod dystrophy and amelogenesis imperfecta." (PMID 31834878, 2019).
colon cancer (1 paper, 2021). "The expression of hsa_circ_0001038 in clinical tissues was also positively correlated with the expression level of metastasis-associated in colon cancer 1 (MACC1) and cyclin-M3 (CNNM3)." (PMID 33841509, 2021).
colorectal cancer (1 paper, 2021). A primary or metastatic malignant neoplasm that affects the colon or rectum. "Conversely, to our knowledge there is no study or dataset reporting a significant correlation between CNNM3 expression and colorectal cancer." (PMID 33923883, 2021).
Infertility (1 paper, 2016). "In this study, we showed that cnnm-1; cnnm-3 mutant worms displayed pleiotropic phenotypes, such as infertility due to a gonadogenesis defect, shortened lifespan, and small body size." (PMID 27564576, 2016).
lung adenocarcinoma (1 paper, 2022). A carcinoma that arises from the lung and is characterized by the presence of malignant glandular epithelial cells. "PDK2 transcriptionally regulated CNNM3 expression in lung adenocarcinoma and conferred the cisplatin resistance." (PMID 36474273, 2022).
cancer (6 papers, 2016 to 2025). A tumor composed of atypical neoplastic, often pleomorphic cells that invade other tissues. "The downregulation of their expression is associated with better prognosis in several cancers, such as XK in ACC, CNNM4 in READ, KEL in CESC, CNNM3 in KIRC, as well as CNNM2 in LGG and KIRC." (PMID 41174507, 2025). "ANKRD36 has been reported to be coexpressing and interacting with other genes on locus 2q11.2, including ANKRD36C, ITPRIPL1, FAHD2B, FAM178B and CNNM3, which shows that ANKRD36 is involved in some important biological networks associated with cancers." (PMID 34827175, 2021). "The CNNM3 D426A mutant has a dominant negative effect on cancer cell proliferation in magnesium-deprived medium." (PMID 26969161, 2016). "In support of this view, it is well established that cancer cells proliferate in a state of hyperpolarized membrane, which correlates with our findings with CNNM3 at −50 mV." (PMID 26969161, 2016). "Hsa_circ 0001038 may bind to miR-337-3p in order to alleviate its inhibition on metastasis-associated in colon cancer 1 (MACC1) and cyclin-M3 (CNNM3), thereby promoting the growth of CC cells and their potential for invasion, respectively, for the purpose of mechanism exploration." (PMID 38341592, 2024). "More recently, CNNM3 and CNNM4 were found to be regulated by PRL phosphatases to increase cellular Mg2+ levels to stimulate cancer cell growth." (PMID 34928937, 2021).
tumor (5 papers, 2015 to 2023). "Concomitantly, we also did not detect any changes in cell current in the presence of CNNM3 D426A, strongly indicating that the contribution of PRL-2 binding in the complex is essential for CNNM3-induced cellular current that will lead to increase tumor growth." (PMID 26969161, 2016). "Remarkably, cells overexpressing the CNNM3 D426A mutant presented reduced tumor size compared with an exponential growth for both empty control and wild-type protein." (PMID 26969161, 2016). "Together, these results demonstrate that the ability of CNNM3 to interact with PRL-2 is essential for tumor progression and that blocking PRL-2·CNNM3 complex formation in vivo causes a growth disadvantage for the tumor cells." (PMID 26969161, 2016). "When PRL-3 interacts with CNNM3, CNNM-dependent magnesium transport is prevented and contributes to cell metabolism leading to tumor progression." (PMID 37220097, 2023).
genetic disease (1 paper, 2016). "Here we observed a decrease in binding of PRL-2 when this corresponding threonine was mutated in CNNM3, suggesting a possible role for PRL in this CNNM-associated genetic disease." (PMID 26969161, 2016).
CNNM3 also shares sentences with these, for which no sentence is quoted: adult-onset Still disease (1 paper); autism (1); clear cell renal cell carcinoma (1); COVID-19 (1); epilepsy (1); Hypertension (1); Jalili syndrome (1); keratosis (1); kidney cancer (1); mental disorder (1); metabolic disorder (1); papillary renal cell carcinoma (1); personality disorder (1); pulmonary disorder (1); retinal cone-rod dystrophy (1); retinitis pigmentosa (1); schizophrenia (1).